CPS1-IT1 (CPS1 intronic transcript 1)
Synonyms: PRO0132; CPS1-IT; CPS1IT; CPS1IT1
Gene: Long non-coding RNA gene on chromosome 2 (210,617,571 to 210,619,876, forward strand). Ensembl gene ENSG00000280837.
Diseases named in the same sentence as CPS1-IT1 in open-access papers:
CPS1-IT1 is named in the same sentence as 3 diseases in open-access papers, as found by Europe PMC text mining. Sharing a sentence is not in itself a finding about the gene and the disease. The quoted sentences say what the papers report.
colorectal cancer (1 paper, 2023). A primary or metastatic malignant neoplasm that affects the colon or rectum. "Some additional studies showed that lncRNA CPS1 intronic transcript 1 (CPS1-IT1) as a positive regulatory factor suppressed cell invasion and metastasis in colorectal cancer, ovarian cancer and LC." (PMID 37938151, 2023).
tumor (1 paper, 2016). "After validation in 119 human HCC tissues, we identified a novel tumor suppressor lncRNA, CPS1 intronic transcript 1 (CPS1-IT1)." (PMID 27248828, 2016). "In this study, we identified a novel tumor suppressor lncRNA, CPS1 intronic transcript 1 (CPS1-IT1), by microarray analysis and subsequently validated this finding in HCC tissue specimens." (PMID 27248828, 2016).
CPS1-IT1 also shares sentences with these, for which no sentence is quoted: ovarian carcinoma (1 paper).